PRSS1 (serine protease 1)
Description:
Has activity against the synthetic substrates Boc-Phe-Ser-Arg-Mec, Boc-Leu-Thr-Arg-Mec, Boc-Gln-Ala-Arg-Mec and Boc-Val-Pro-Arg-Mec. The single-chain form is more active than the two-chain form against all of these substrates.
Synonyms: TRP1; TRY1; TRYP1; TRY4
Tractability: Small molecule: a structure with a bound ligand is known; a high-quality ligand is known; it has a binding pocket of medium quality; it belongs to a druggable protein family. Antibody: its Gene Ontology location is reachable by antibodies, with high confidence; UniProt places it where antibodies can reach, with medium confidence; UniProt predicts a signal peptide or a membrane-spanning region. PROTAC: ubiquitination databases record sites on it; a small molecule that binds it is known.
Target class: Serine protease; Enzyme; Serine protease PA clan; Serine protease S1A subfamily; Protease
Gene: Protein-coding gene on chromosome 7 (142,749,468 to 142,753,072, forward strand). Ensembl gene ENSG00000204983.
Subcellular location: Secreted, extracellular space
Subcellular location (Human Protein Atlas): Vesicles; Endoplasmic reticulum; Predicted to be secreted
Pathways (Reactome):
Developmental Biology: Developmental Lineage of Pancreatic Acinar Cells
Extracellular matrix organization: Activation of Matrix Metalloproteinases
Metabolism: Uptake of dietary cobalamins into enterocytes
Gene Ontology:
Molecular function: serine-type endopeptidase activity
Biological process: extracellular matrix disassembly; proteolysis
Cellular component: blood microparticle; extracellular matrix; extracellular region
Genetic constraint (gnomAD): Loss-of-function variants: 24 observed, 25.94 expected, observed/expected ratio (o/e) 0.93, 90% interval 0.67 to 1.3. The upper end of that interval is the gene's LOEUF score, 1.3, which puts it in group 5 of 6, group 1 being the genes least tolerant of losing a copy. Missense variants: 366 observed, 292.88 expected, observed/expected ratio (o/e) 1.25, 90% interval 1.15 to 1.36. Synonymous variants: 126 observed, 106.95 expected, observed/expected ratio (o/e) 1.18, 90% interval 1.02 to 1.37.
Gene-disease validity (ClinGen):
ClinGen rates the evidence that PRSS1 causes each of these diseases.
hereditary chronic pancreatitis (autosomal dominant): Definitive. Hereditary chronic pancreatitis (HCP), a rare inherited form of pancreatitis is defined as recurrent acute pancreatitis and/or chronic pancreatitis in two first-degree relatives or 3 or more second-degree relatives in 2 or more generations, for which no predisposing factors are identified.
Homologues: Orthologues: chimpanzee PRSS1 (97% identical), pig PRSS2 (79% identical), mouse Try10 (78% identical), rat Prss2 (78% identical), rat Prss2l1 (77% identical), mouse Prss3l (77% identical), mouse Try4 (77% identical), mouse Prss1 (76% identical), mouse Prss3 (76% identical), mouse Prss1l (76% identical), mouse Try5 (76% identical), rat Prss1 (76% identical), and 6 more. Paralogues in human: PRSS2 (89% identical), PRSS3 (85% identical), PLAU (40% identical).
Diseases named in the same sentence as PRSS1 in open-access papers:
PRSS1 is named in the same sentence as 103 diseases in open-access papers, as found by Europe PMC text mining. Sharing a sentence is not in itself a finding about the gene and the disease. The quoted sentences say what the papers report.
pancreatitis (81 papers, 2007 to 2025). Inflammation of the pancreas. "In contrast to adults, the primary etiological drivers of pancreatitis in pediatric populations include infections (e.g., mumps virus), adverse drug reactions (e.g., valproic acid), and genetic predisposition (e.g., PRSS1 gene mutations)." (PMID 41426674, 2025). "Increased trypsinogen autoactivation initiating autodigestion and inflammation is the primary mechanism by which gain-of-function mutations in PRSS1 cause pancreatitis." (PMID 40230746, 2025). "Variants and/or mutations in the PRSS1 gene have been found to be associated with pancreatitis and pancreatic adenocarcinoma." (PMID 40382561, 2025). "Genetic factors, including mutations in the cystic fibrosis transmembrane conductance regulator gene (CFTR) and cationic trypsinogen gene (PRSS1), are rare causes of pancreatitis." (PMID 40376315, 2025). "We report a case involving false-positive variant calls in PRSS1 identified by NGS in a pediatric patient with pancreatitis." (PMID 40861062, 2025). "Lifetime risk for PC is increased for PRSS1 PGV carriers who display a pancreatitis phenotype, with lifetime risk for PC estimated to be 44–52%." (PMID 39932614, 2025). "For example, gain-of-function mutations in the cystic fibrosis transmembrane conductance regulator (CFTR) gene and cationic trypsinogen gene (PRSS1) are commonly associated with the development of pancreatitis." (PMID 41378273, 2025). "Pathogenic mutations in both the CTRC and PRSS1 genes have been associated with pancreatitis, where oxidative stress significantly contributes to inflammation in the pancreas and exacerbates pain pathways." (PMID 41158431, 2025). "Hereditary/genetic pancreatitis is caused by a mutation in the gene that encodes cationic trypsinogen (protease serine 1, or PRSS1) and is mapped to 7q35 on the long arm of human chromosome 7." (PMID 39896151, 2024). "The T7K24R mouse strain carries the p.K24R mutation in mouse cationic trypsinogen (isoform T7), which is analogous to the p.K23R pancreatitis-associated human PRSS1 mutation." (PMID 36136430, 2022). "Compared with children without gene mutations, children with gene mutations associated with pancreatitis have a higher risk for CP and pancreatitis progression rate, especially those with PRSS1 gene mutation." (PMID 35958176, 2022). "At least five genes have been identified to be associated with pancreatitis: serine protease 1 (PRSS1), serine peptidase inhibitor Kazal type 1 (SPINK1), CFTR, chymotrypsin C (CTRC), and calcium sensing receptor (CASR)." (PMID 35844741, 2022). "Hereditary pancreatitis (HP) has been defined as pancreatitis occurring in 2 or more individuals in a family for 2 or more generations or pancreatitis associated with a mutation in the cationic trypsinogen PRSS1 (protease serine 1) gene." (PMID 35761384, 2022). "The T7D23A mouse strain carries the p.D23A mutation in mouse cationic trypsinogen (isoform T7), which is analogous to the p.D22G pancreatitis-associated human PRSS1 mutation." (PMID 36136430, 2022). "The genetic factors leading to pancreatitis have been studied extensively and several genes such as SPINK1, CFTR, HLA‐DRB*0401, and PRSS1 have been attributed with the increase in predisposition to develop pancreatitis." (PMID 35340657, 2022). "T7D23A and T7K24R mice carry the p.D23A and p.K24R mutations in mouse T7 trypsinogen, which are analogous to the human pancreatitis-associated PRSS1 mutations p.D22G and p.K23R, respectively." (PMID 36136430, 2022). "Remarkably, in their 2020 publication, the Ji group reported that the anticoagulant dabigatran etexilate markedly improved cerulein-induced pancreatitis in transgenic mice carrying human PRSS1 with the p.R122H mutation (named PRSS1R122H mice by the authors)." (PMID 36136430, 2022).
pancreatitis (continued). "The identification of activating pathogenic variants in cationic trypsinogen gene PRSS1 (a precursor of major pancreatic digestive enzyme) in hereditary pancreatitis supported the classical theory of pancreatitis as an autodigestive disease." (PMID 34065437, 2021). "Currently, HP has been defined as either two or more individuals within a family exhibiting pancreatitis for two or more generations, or pancreatitis linked to mutation of the PRSS1 gene." (PMID 33375361, 2020). "The results also caution that analysis of the PRSS1 gene in patients with suspected genetic predisposition for pancreatitis should include all five exons and exon–intron junctions, so that rare pathogenic variants such as p.Glu190Lys are not overlooked." (PMID 30792736, 2019). "The pancreatitis protective T allele of rs10273639 that is associated with less PRSS1 expression is a risk allele for meconium ileus." (PMID 30807572, 2019). "Studies spanning almost two decades revealed that PRSS1 mutations cause pancreatitis via two different mechanisms; the trypsin-dependent and the misfolding dependent pathways (Hegyi and Sahin-Tóth, 2017; Sahin-Tóth, 2017)." (PMID 30792736, 2019). "The first gene related to pancreatitis was the cationic trypsinogen gene protease serine 1 (PRSS1) in 1996: a gain of function missense mutation i.e., the R122H, was identified as a risk factor for CP." (PMID 30134826, 2018). "Our finding is consistent with the meta-analysis conducted by Liu and Zhang which suggested a significant association between total pancreatitis and the PRSS1 gene." (PMID 29118810, 2017). "A T to C substitution at rs10273639, in the noncoding region of PRSS1-PRSS2 locus (near the PRSS1 gene), is associated with recurrent pancreatitis and CP by influencing the expression of PRSS1." (PMID 29333155, 2017). "Mutations in the human PRSS1 gene are associated with pancreatitis and have provided insight into the pathogenesis of the disease." (PMID 25667658, 2015). "To date, several pancreatitis-associated genes have been identified such as the cationic trypsinogen (PRSS1) gene and the serine protease inhibitor, Kazal type 1 (SPINK1) gene have been identified." (PMID 25157235, 2014). "Hereditary pancreatitis is a rare autosomal dominant condition caused by gain-of-function mutations in the cationic trypsinogen gene (PRSS1) and is responsible for <1% of all forms of pancreatitis." (PMID 24474940, 2013). "Both mouse models were more susceptible to caerulein-induced pancreatitis developing more severe pancreatitis underscoring the importance PRSS1 mutations as a pathogenic mediator." (PMID 22133269, 2011). "Excluding PRSS1, other genes act as predisposing factors that are associated with environmental and metabolic factors, such as alcohol and hyperlipidemia, lowering the threshold for pancreatitis." (PMID 40230746, 2025). "The p.A16V and p.N29I mutations, both high-penetrance PRSS1 pathogenic variants, may contribute to the multigenic inheritance of a predisposition to pancreatitis." (PMID 40861062, 2025). "The patient was enrolled to the study on September 16, 2024 with the following diagnosis: hereditary painful pancreatitis (heterozygous mutation of the PRSS1 gene), continuously recurring disease form (7 or more attacks per year during the period from 2001 to 2024)." (PMID 39896151, 2024). "However, gain-of-function or mutations that cause misfolding of cationic trypsinogen (PRSS1) lead to its premature intrapancreatic activation, causing autodigestion of the pancreas and pancreatitis." (PMID 36699452, 2022). "Interestingly, we found no mutations that passed quality control or the expected segregation pattern, in genes known to be associated with pancreatitis such as PRSS1, CFTR, SPINK, CPA1, CTRC, CLDN2, and PLINP." (PMID 36699452, 2022).
pancreatitis (continued). "In the 2019 clinical diagnostic criteria for CP, mutations in established pancreatitis-associated genes, such as PRSS1 and SPINK1, are included in the diagnostic items for early stage CP, and the role of genetic testing in daily clinical practice is increasing." (PMID 35994093, 2022). ",33, 34, 35, 36 Although genetic factors such as mutations of cationic trypsinogen gene (PRSS1) are strongly associated with pancreatitis, acinar cells may develop adaptive response to protect against insults from alcohol abuse and other environmental factors." (PMID 31987928, 2020). "However, as PRSS1 variants are associated with early‐onset pancreatitis, they are possibly underrepresented in the present data set owing to the exclusion of studies performed exclusively in paediatric populations." (PMID 32011822, 2020). "Therefore, we always use very specific methods to confirm true mutations in the PRSS1 genes when analyzing patients at risk for pancreatitis." (PMID 23230421, 2012). "However, the proportion of PRSS1-related pancreatitis cases caused by de novo pathogenic variants remains unknown." (PMID 40230746, 2025). "It's noteworthy here that mutations in PRSS1 gene have been reported to possibly cause increased intra-acinar trypsin levels, thereby increasing the risk of auto-digestion leading to pancreatic inflammation, pancreatitis, and increased risk of pancreatic cancer." (PMID 40382561, 2025). "Pathogenic variants of the SPINK1 and PRSS1 genes have the maximum impact on the risk of CP development in patients from different countries, as the products of these genes are key participants in the trypsin-dependent pathogenetic pathway of the pancreatitis development." (PMID 37389024, 2023). "We investigated the expression of pancreatitis-associated genes with the ability to act as positive regulators of the IL-6 amplifier; these genes include GGT1, PRSS1, CASR, CTRB1, ABO, SPINK1, and CTRC." (PMID 38806529, 2024). "Individuals who underwent germline multigene testing for pancreatitis susceptibility genes (CASR, CFTR, CPA1, CTRC, PRSS1, SPINK1) through a large commercial laboratory between 2017 and 2022 were included." (PMID 39172977, 2024). "So far, several genes with potential application in the diagnosis of pancreatitis have been described, including PRSS1, CFTR, CTRC, and SPINK1." (PMID 39457082, 2024). "Next Generation Sequencing was performed to analyze a panel of nine genes associated with pancreatitis (CaSR, CFTR, CPA1, CTRC, CTSB, KRT8, PRSS1, PRSS2, and SPINK1)." (PMID 38927485, 2024). "PRSS1, serine peptidase inhibitor Kazal type 1 and chymotrypsin C are specifically or highly expressed in the acinar cells of a patient with pancreatitis." (PMID 37682188, 2023). "Mutations in PRSS1, SPINK1, CTRC, CASR, and CFTR were linked with pancreatitis and pancreatic cancers when the molecular basis of pancreatitis was investigated." (PMID 36434531, 2022). "Four patients (4.1%), 3 (3.1%) with a SPINK1 c.194 + 2T>C variation and 1 (1.0%) with a PRSS1 p.Arg122His variation, experienced multiple recurrent pancreatitis episodes after surgical resection for chronic pancreatitis." (PMID 35171259, 2022). "We note that future clinical trials of trypsin inhibitors in pancreatitis should focus on PRSS1-related hereditary pancreatitis and other trypsin-mediated forms of the disease." (PMID 36136430, 2022). "Genetic factors including mutations in CFTR, PRSS1, SPINK1 genes play an important role among the causes of acute, recurrent pancreatitis." (PMID 33652736, 2021). "The ratio of PRSS1 and its inhibitor SERPINA1 or alpha-1-antitrypsin is elevated in patients with PDAC, and SERPINA1 deficiency is associated with pancreatitis and cachexia phenotypes." (PMID 33334063, 2020). "The keyword search (PRSS1 and Pancreatitis) via PubMed resulted in 173 entries starting from the pioneering Whitcomb study." (PMID 33202925, 2020).
pancreatitis (continued). "Germline testing, currently for recommended etiologic mutations associated with pancreatitis, includes evaluation for pathogenic variants in the CEL, CFTR, CPA1, CTRC, PRSS1, and SPINK1 genes in symptomatic individuals." (PMID 33375361, 2020). "This notion is also supported by the genetic evidence that mutations in cationic trypsinogen (PRSS1), pancreatic secretory trypsin inhibitor (SPINK1), and chymotrypsinogen C (CTRC) are associated with the susceptibility of pancreatitis." (PMID 25140315, 2014). "The present report focuses on the finding of a new heterozygous mutation in the PRSS1 gene, associated with p.F508del mutation in CFTR, in a child presenting acute recurrent pancreatitis." (PMID 20950468, 2010). "Therefore, we cannot exclude the possibility of undetected second CFTR variants, modifier alleles, or other pancreatitis‐associated gene variants (i.e., SPINK1, PRSS1, or CTRC)." (PMID 40468859, 2025). "Elevated ER stress is an important mechanism of pancreatitis in humans, as shown by the accumulation of misfolded PRSS1 leading to hereditary chronic pancreatitis, and may lead to a reduction in acinar cell protein synthesis and ultimately cell death." (PMID 41312553, 2025). "In a previous case report, loss-of-function PRSS1 variant p.Y37X was found in chronic alcoholics without pancreatitis." (PMID 40230746, 2025). "Overall, compared to normal children, previous studies have demonstrated the association of SPINK1 and PRSS1 with ARP and CP; nonetheless, using children with ARP as a reference in this study, PRSS1 mutations were more closely associated with CP and pancreatitis progression than SPINK1 mutations." (PMID 35958176, 2022). "The patient did not have known pancreatitis-associated mutations, such as PRSS1, SPINK1, CTRC, CPA1, or TRPV6." (PMID 36419930, 2022). "The findings reported by the INSPPIRE were that at least one pancreatitis-related gene mutation was found in 48 and 73% of ARP and CP patients, respectively, and SPINK1 and PRSS1 mutations were more closely related to CP, and children with ARP with pathogenic PRSS1 variants rapidly progress to CP." (PMID 35958176, 2022). "Children with PRSS1 gene mutations have a faster rate of progression to CP; however, PD does not affect the disease progression rate to CP, and ERCP appears to provide a benefit in delaying progression to CP in children with PD with recurrent pancreatitis." (PMID 35958176, 2022). "We did not observe mutations or CNVs in PRSS1, or mutations in other genes that are associated with pancreatitis, in this study." (PMID 36699452, 2022). "The aetiology of paediatric pancreatitis, which includes infections, systemic diseases, trauma, drug induction, biliary system diseases, anatomical abnormalities and genetic cause (CFTR, PRSS1, SPINK1, CTRC mutations), is significantly different from that of adults." (PMID 34178894, 2021). "Case 1: Eight months old female child suffering from constipation, recurrent vomiting and failure to thrive, family history of recurrent pancreatitis without mutations in the PRSS1 and SPINK1 genes." (PMID 33990208, 2021). "PRSS1 is exclusively expressed in the exocrine pancreas and was previously associated with non-CF pancreatitis with functional characterization demonstrating impact on PRSS1 gene expression." (PMID 30807572, 2019). "PRSS1 and other pancreatitis-associated gene mutations are not directly important in the development of pancreatic cancer, but rather lead to a high-risk inflammatory milieu for the accumulation of oncogenic mutations." (PMID 24600409, 2014). "In addition to PRSS1, CFTR, and SPINK1, the CTRC and CASR genes are additional risk factors that appear to increase risk of pancreatitis in the context of one of three primary susceptibility factors." (PMID 23230421, 2012).